IGFBP2 (insulin like growth factor binding protein 2)
Diseases named in the same sentence as IGFBP2 in open-access papers (continued):
Sharing a sentence is not in itself a finding about the gene and the disease.
cancer (220 papers, 1996 to 2026). A tumor composed of atypical neoplastic, often pleomorphic cells that invade other tissues. "The ICBatlas analysis revealed the conserved bidirectional pattern (protective MAOB/SERPINA1 vs. risk-enhancing IGFBP2/LGR6) of the four-gene signature as a pan-cancer theoretical framework for risk stratification." (PMID 40821817, 2025). "Previous studies demonstrated that abnormal expression patterns of IGFBP2 are detectable in various human cancers and are significantly associated with poor prognosis." (PMID 40728947, 2025). "Then, the same mutational analysis was performed for cancer types exhibiting upregulation of IGFBP2, including BRCA (0.5%), GBM (0.3%), HNSC (1.6%), LUAD (0.6%), PRAD (1.1%), THCA (0%), and UCEC (1.6%)." (PMID 39854135, 2025). "In both cases, it was unexpectedly discovered that IGFBP2 displayed a mutation rate that was nearly identical with a minimal percentage of mutation in different types of cancers." (PMID 39854135, 2025). "IGSF9 and IGFBP2 are implicated in multiple cancers and are considered potential diagnostic or prognostic markers and treatment targets." (PMID 41071435, 2025). "Conversely, IGFBP-2, while capable of binding IGFs, is frequently associated with tumorigenic behaviors, including increased migration, invasion, and survival of cancer cells, particularly via IGF-independent mechanisms." (PMID 39585162, 2024). "Together, these data are supportive of lower stromal IGFBP2 expression correlating with age-related cancer risk and disease progression." (PMID 37436978, 2023). "Of these eight PRS genes, three (BMP5, TNFRSF11B, and IGFBP2) are immune-related genes, and their association with the prognosis of cancer patients has been previously reported." (PMID 35535221, 2022). "A literature‐based survey clearly shows that the association between IGFBP2–3 and cancer was widely studied, while less studies were done on the remaining IGFBP family members (IGFBP1, IGFBP4, IGFBP5, and IGFBP6)." (PMID 35546443, 2022). "This makes it possible to use a risk prediction model of including IGFBP2 to forecast prognosis of cancer patients." (PMID 35546443, 2022). "In conclusion, there is growing evidence that IGFBP2 is associated with cancer-related immune responses." (PMID 35992105, 2022). "Among many biomarkers of cancer, IGF-2 and IGFBP-2 expression is upregulated in many types of cancer and is associated with an increased risk of developing cancers therefore frequently considered as neoplastic marker." (PMID 34899612, 2021). "During the last two decades, IGFBP2 has been reported to be aberrantly expressed in a broad range of cancers and associated with the promotion of several key oncogenic processes." (PMID 34830078, 2021). "The evidence showed that the IGFBP2 levels are associated with cancer cell invasion and metastasis; instead, IGFBP7 displays an ambiguous activity as an oncogene or suppressor gene in distinct types of cancers." (PMID 34440012, 2021). "Overexpression of intracellular IGFBP2 has been described in several human cancers where it is associated with cellular proliferation, progression and drug-resistance." (PMID 30626422, 2019). "In the study, we demonstrate that IGFBP2 promotes the phosphorylation of FcγRIIB on cancer exposed immune cells, which is associated with its mesenchymal induction." (PMID 31560714, 2019). "Of all the six similar IGFBPs, IGFBP-2 has most frequently been reported to be overexpressed in a range of human cancers and only IGFBP-2 has been linked to the DNA-DSB repair pathway." (PMID 29163372, 2017). "The expression of IGFBP-2 is positively associated with tumour progression in various types of cancers." (PMID 29088813, 2017).
cancer (continued). "Both findings point towards higher insulin sensitivity, in the case of IGFBP-2 also towards a reduced cancer risk." (PMID 24236134, 2013). "Furthermore, the macrophages were divided into four different subtypes, and cell–cell communication analysis unveiled that IGFBP2+ cancer-associated fibroblasts demonstrated the most robust interactions with SPP1+ macrophages." (PMID 41262519, 2026). "High levels of IGFBP‐2 can be explained by its involvement in neural development, growth, and activity, while in GB patients, increased expression of the IGF signaling axis, for example, IGFBP‐2 secretion, has been associated with malignant tumor progression and TMZ resistance." (PMID 40277152, 2025). "In addition to its role in cancer biology, IGFBP2 has been studied in pregnancy-associated disorders." (PMID 40728947, 2025). "Finally, IGFBP2 is also a component of the senescence-associated secretory phenotype associated with increased aggressiveness in cancer, and senescence and aging are often linked." (PMID 39007351, 2024). "High expression of IGFBP-2 in cancer tissues has been associated with a worse outcome." (PMID 38255230, 2024). "IGFBP2 is significantly associated with poor prognosis in some cancers and metabolic diseases and could promote angiogenesis, tumorigenesis, and metastasis." (PMID 38443392, 2024). "Additionally, IGFBP2 has been associated with resistance to chemotherapy and radiation therapy in certain cancers." (PMID 37928523, 2023). "IGFBP-2 holds potential as a therapeutic target in cancer, and circulating levels might be useful as diagnostic and prognostic biomarkers." (PMID 38137505, 2023). "Therefore, we performed the meta‐analysis to assess the association between IGFBP2 expression and the survival outcomes and the prognostic significance of the IGFBP2 in cancer patients, searched from 21 literature studies containing 5560 patients." (PMID 35546443, 2022). "The meta‐analysis showed that IGFBP2 expression was associated with worse prognosis in several tumors, and may serve as a potential prognostic biomarker in cancer patients." (PMID 35546443, 2022). "Notably, IGFBP2 has been associated with chemoresistance in cancer cells, e.g., by inducing an EMT program in pancreatic or other cancer cells, respectively." (PMID 34830078, 2021). "Thus, the study applied a syngeneic mouse GBM model, human GBM samples, and cancer-immune cell co-culture experiments to investigate the effect of IGFBP2 on GBM exposed immune cells and its association with the mesenchymal induction." (PMID 31560714, 2019). "Despite the role of IGFBP2 in tumorigenesis, the mechanisms underlying IGFBP2 contribution to the tumorigenic program in cancer remain unknown, especially in LAM and other hormone-dependent tumors." (PMID 28410230, 2017). "IGFBP-2 has been demonstrated to be associated with metastasis in various cancers." (PMID 28977895, 2017). "We have also investigated whether IGFBP2 expression is regulated in other cancers associated with HPV infection." (PMID 26107517, 2015). "High levels of IGFBP2 have been associated with poor prognosis in several cancer types." (PMID 26097693, 2015). "Further studies with larger sample size from different type of cancer will be performed to confirm and validate whether anti-IGFBP-2 antibodies can be also used as a diagnostic marker in other type of cancer." (PMID 23165420, 2013). "Elevated expression of IGFBP-2 is often associated with progression of many types of cancers." (PMID 19081843, 2008). "This IGFBP2 loss in the breast tissue microenvironment upon disease progression highlights that investigation of healthy stromal cells may provide key insights into the mechanisms of tissue homeostasis that is disrupted in cancer." (PMID 37436978, 2023).
cancer (continued). "For example, circulating IGFBP1 and IGFBP2 appear to be involved in regulating acute bioavailability of IGFs, and when their expression is inhibited, they may increase the mitogenic activity, thereby increasing the risk of cancer." (PMID 37088808, 2023). "Taken together, as the recruitment of innate and adaptive immunity to initiate a more integrated immune response to cancer is the best way to immunotherapy, targeting the IGFBP2-FcγRIIB pathway may enhance the susceptibility of mesenchymal GBMs to various immunotherapeutic regimens." (PMID 31560714, 2019). "Two genes, Igfbp5 and Igfbp2, residing in this locus and belonging to the insulin-like growth factor binding protein family were expressed at significantly greater levels in normal lung tissue from cancer-resistant Car-R mice than in cancer-susceptible SWR/J mice." (PMID 22973541, 2012). "For the second type of change, miR-125b-high altruistic cancer cells can secrete higher levels of diffusible proteins (IGFBP2 and CCL28) that not only confer benefits but also discourage neighboring cells from turning into altruistic cells." (PMID 39774289, 2025). "It is important to mention that metastatic cancer cells secrete insulin-like growth factor binding protein-2 (IGFBP-2), a biomarker of human metastasis, which makes IGF-1 available in endothelial cells and activates the IGF-1 pathway." (PMID 41153350, 2025). "A comprehensive RNA-Seq analysis revealed significant mRNA upregulation of several genes, including ACTA1, IGFBP2, MUC5B, CEACAM5, and KRT19, all of which are associated with cancer progression in various types of malignancies (p < 10−10)." (PMID 40004774, 2025). "More recently, efforts are being made to exploit the IGF system by particularly targeting IGFBP-2, which is gaining attention due to its presence in cancer cells and absence in normal mature brain cells." (PMID 40634830, 2025). "miR-126, a microRNA that suppresses metastatic endothelial recruitment, targets, among others, IGFBP-2, and it was found to be downregulated in several cancer types, thus promoting the metastatic phenotype." (PMID 41153350, 2025). "Emerging research evidence indicates that abnormal expression of IGFBP2 in cancer acts is a crucial step in the carcinogenic network by integrating various cancer signaling pathways." (PMID 40728947, 2025). "A key mediator is IGFBP2, upregulated in several cancers and involved in processes such as EMT, angiogenesis, and invasion via β-catenin and STAT2 signaling, contributing to the malignancy." (PMID 41226816, 2025). "Insulin-like growth factor-binding protein 2 (IGFBP-2), which binds IGF-2, is linked to cancer metastasis through its interaction with HSP27." (PMID 40806747, 2025). "The integrin/ILK/NF-κB, IGF1R/PI3K/AKT, and Wnt/β-catenin pathways, as well as certain micro-RNAs have been proven to regulate or be regulated by IGFBP2 in a variety of malignant tumors." (PMID 39221034, 2024). "Insulin-like growth factor binding protein 2 (IGFBP2) belongs to IGFBP family which has attracted increasing attention for the critical roles in various cancers." (PMID 38918360, 2024). "Because of its role in cell proliferation, IGFBP-2 has been studied mainly in different types of cancer." (PMID 38255230, 2024). "Previous studies suggested IGFBP2 as a key inducer of epithelial--mesenchymal transition (EMT) in many malignant cancers, making it a potential immunotherapy target in mesenchymal GBM." (PMID 38339384, 2024). "IGFBP2 has been extensively studied as a secreted protein or cytoplasmic signaling effector in cancer cells in many malignant cancers." (PMID 40625452, 2024). "Consistent with The Cancer Genome Atlas (TCGA) data, IGFBP2 was also significantly upregulated in cancer tissues, compared with corresponding paracancerous tissues as detected by qRT-PCR and IHC assay." (PMID 38918360, 2024).
cancer (continued). "Accumulating evidence indicates that high expression of IGFBP2 promotes tumorigenesis, progression, and chemotherapy resistance in many malignant tumors." (PMID 38268050, 2024). "IGFBP2 and the functionality of cancer cells are intimately connected, according to numerous studies." (PMID 38316422, 2024). "IGFBP-2 is a member of the IGFBPs family, with a potential role as a biomarker for several malignant tumors." (PMID 39201667, 2024). "In human NB cell lines, IGFBP‐2 enhances the proliferation and invasion of adult NB cells and is also an activator of invasive behavior in cancer cells." (PMID 40625452, 2024). "Our study describes an anti-invasive mechanism in which autocrine proinvasive IGF-II signaling by cancer cells is disrupted by IGFBP2 acting as a stromal sequester of IGF-II." (PMID 37436978, 2023). "Increased expression of IGFBP-2 in PDAC affects the invasion of cancer cells and the formation of metastases by influencing the NF-κB-dependent epithelial–mesenchymal transition." (PMID 37373743, 2023). "As an mRNA binding protein, IGFBP2 plays a crucial role in cancer development and progression by regulating mRNA stability and localization." (PMID 37952076, 2023). "Differences in circulating IGF-1 and its inhibitors (IGFBP-2 and IGFBP-3) have been associated with the risk of several cancers, thus proposing these indicators as non-invasive biomarkers for cancer risk and prognosis." (PMID 38137390, 2023). "Overall, our results implicate the trophic factors CCL28 and IGFBP2 in mediating the fitness benefits conferred by the miR-125bHigh altruistic cancer cells." (PMID 38093346, 2023). "Numerous studies have demonstrated the crucial role of IGFBP2 in promoting pathologic angiogenesis in various cancer types." (PMID 38124748, 2023). "The prognostic significance of insulin‐like growth factor binding protein 2 (IGFBP2) expression has been explored in plenty of studies in human cancers." (PMID 35546443, 2022). "The strength of our study was to systematically collect evidence on the prognostic value of IGFBP2 in cancer patients." (PMID 35546443, 2022). "When IGFBP2 was overexpressed, the cancer patients in these studies had a poor prognosis within all methods." (PMID 35546443, 2022). "In cancer cells, IGFBP2 expression is topologically imported into the cytoplasm and the nucleus is absent of a nuclear localization sequence." (PMID 36142846, 2022). "More prospective studies of large number of patients are needed to further confirm the value of IGFBP2 in various cancers." (PMID 35546443, 2022). "Recently, increasing studies have indicated that IGFBP2 plays a critical effect on tumorigenesis through modulation of some cancer characteristics." (PMID 35546443, 2022). "In this meta‐analysis, we conducted the quantitative analysis to evaluate the relationship between IGFBP2 expression and prognosis in various cancer patients." (PMID 35546443, 2022). "DORexo contained enhanced levels of IGF-2 and IGFBP2, and we are wondering if the promotive effect of BMSCs on cancer cell growth in bone marrow is through activating IGF-1R." (PMID 36568212, 2022). "The transfer of IGF-2 and IGFBP2 from cancer cells to BMSCs enhanced the glycolysis of BMSCs, supporting cancer cell survival in the bone marrow through the production of lactic acid." (PMID 36568212, 2022). "In EAC cells (OE33, OE19, FLO-1) exposed to 200 μM of acidified BM for 20 min, enhanced cancer cell survival was noted due to EGFR-DNA-PKcs pathway activation via insulin-like growth factor binding protein 2 (IGPBP2)." (PMID 35328735, 2022). "The cellular localization of IGFBP2 at the colonic crypts of normal mucosa and the higher expression levels in cancer tissues refer also to a role of IGFBP2 in stem cell formation." (PMID 34830078, 2021). "Namely, IGFBP2 promotes cancer cell evasion, metastasis, cancer stem cell expansion, and angiogenesis." (PMID 32093404, 2020).
cancer (continued). "siRNA also indicated that the relationship between FOXA1 and IGFBP-2 in cancer cells was different, as although silencing FOXA1 reduced levels of IGFBP-2, the ratio of FOXA1 to IGFBP-2 appeared to remain the same." (PMID 32655839, 2020). "It is well established that IGFBP-2 is upregulated in many cancers including the prostate and this was observed in our own tissue cohort." (PMID 32655839, 2020). "The overexpression of IGFBP-2 has been shown to correlate with tumor progression in a number of cancers, including ovarian, lung, and pancreatic cancer." (PMID 32911852, 2020). "In order to further discriminate between cancer patients and controls, ROC curves were generated using plasmatic values of IGFBP2 and anti-IGFBP2 antibodies." (PMID 32093404, 2020). "Overexpression of Insulin-like growth factor binding protein 2 (IGFBP2) has been reported to be involved in the progression of many types of cancer." (PMID 32296458, 2020). "With the cancer cells, CHiP analysis indicated that the level of FOXA1 associating with the IGFBP2 gene was minimal in comparison to the normal cells." (PMID 32655839, 2020). "To date, most of reports described expression and function of IGFBP2 in a variety of cancers, where it is highly expressed and modulates the mitogenic IGF functions in the intercellular space." (PMID 32302288, 2020). "Our results indicate that polyploid ASC.B6 cells activate the pro-survival pathway in 4T1 cancer cells by changing the balance of their paracrine factors, namely, by downregulating IGFBP2 and secreting IGF1." (PMID 32133294, 2020). "ANXA1 was also found to be correlated with IGFBP2 (insulin-like growth factor-binding protein 2), a circulating biomarker for cancer diagnosis and a potential immunotherapeutic target, also belonging to the gene signature identified by Model II." (PMID 32070274, 2020). "There are mixed reports on the role of insulin-like growth factor binding protein-2 (IGFBP-2) in cancer progression." (PMID 31903164, 2019). "We next, investigated the role of IGFBP2 upregulation in protecting cancer cells from excessive ABS-induced DNA damage and apoptosis." (PMID 30626422, 2019). "As the mesenchymal traits are tightly related to immunosuppression in cancer, we then examined the effect of IGFBP2 on immune cells exposed to GBM cells by using the GL261-SPCs co-culture experiments and the mouse GBM model." (PMID 31560714, 2019). "High levels of IGFBP2 have been detected in patients’ sera of some cancers with poor prognostic outcome." (PMID 30626422, 2019). "IGFBP2 is a secretory protein with high levels in the serum of patients with several types of cancer." (PMID 30626422, 2019). "Taking this data together with observations in the cancer literature, we propose a model in which Pitpnc1a stimulates the secretion of inhibitory IGFBP2 that acts as an IGF counterbalance onto circuits involved in wakefulness." (PMID 30089250, 2018). "Unlike IGFBP3, which induces antitumor activity in different types of cancers, IGFBP2 promotes tumorigenesis, cancer cell invasion, metastasis, and cancer stem cell expansion." (PMID 28036255, 2017). "Wound healing, migration and invasion assays revealed that knockdown of IGFBP-2 inhibits cancer cell migration and invasion." (PMID 28977895, 2017). "It has been reported that serum insulin-like growth factor-binding protein 2 (IGFBP2) levels are elevated in various types of cancers." (PMID 28036255, 2017). "This is consistent with the data that shows the involvement of IGFBP-2 in altered sensitivity of cancer cells to chemotherapy when IGFBP-2 expression is silenced." (PMID 29088813, 2017). "Abrogation the expression of IGFBP-2 in experimental models of cancer types would significantly inhibit cell proliferation, migration and invasion." (PMID 28410230, 2017).